PTX3 (pentraxin 3)
Diseases named in the same sentence as PTX3 in open-access papers (continued):
Sharing a sentence is not in itself a finding about the gene and the disease.
Klebsiella pneumonia (1 paper, 2015). An pneumonia caused by infection with Klebsiella. "Nevertheless, PTX3 expression has also been associated with exacerbated inflammatory responses and disease outcomes in intestinal ischemia-reperfusion injury and pulmonary infection with Klebsiella pneumonia." (PMID 25695775, 2015).
Krabbe disease (1 paper, 2022). A lysosomal disorder that affects the white matter of the central and peripheral nervous systems. "In keeping with these observations, twitcher mice, an authentic model of Krabbe disease, were characterized by the progressive upregulation of PTX3 along the CNS caudal-rostral axis, with no changes in the peripheral organs." (PMID 36012705, 2022).
Lyme neuroborreliosis (1 paper, 2023). "CSF PTX3 in patients with Lyme neuroborreliosis had significantly increased levels of PTX3 compared to the control group (p = 0.005)." (PMID 36862691, 2023).
lymphedema (1 paper, 2023). Excess fluid collection in tissues, causing swelling. "Furthermore, we identified significant similarities in the fibrotic features of PACs between CrF and SAT in lymphedema, including the up-regulation of PTX3, a fibrosis-associated marker, as well as specific cell-to-cell interactions involving ANNEXIN, LIGHT, CCL, and PDGF." (PMID 38111581, 2023). "Co-analyzing the data from patients with lymphedema, we found that pro-fibrotic PACs featured upregulated pentraxin-3 expression, suggesting a potential target for the treatment of fibrosis in CrF." (PMID 38111581, 2023). "This suggests that the up-regulated expression of PTX3 is a distinct characteristic of creeping fat and fibrotic adipose tissue in lymphedema." (PMID 38111581, 2023). "Also, we found the similarities between PACs in CrF and lymphedema in fibro-genic features with pentraxin-3 expression and cell-to-cell interactions." (PMID 38111581, 2023).
lymphopenia (1 paper, 2021). Reduction in the number of lymphocytes. "These include: lymphopenia; neutrophilia; neutrophil activation; increased intermediate and non-classical monocytes; high CD64 expression on monocytes and neutrophils; and raised levels of IL-6, IL-18, PAI-1, sCD25, sTNF-R, IP-10, MPO, and PTX3." (PMID 34632327, 2021).
macular degeneration (1 paper, 2016). Loss of vision in the central portion of the retina (macula), secondary to retinal degeneration. "Again, based on the interaction between PTX3 and complement factor H that contribute to maintain the retinal immunohomeostasis, the stimulation of PTX3 could reduce the pathophysiology of macular degeneration." (PMID 27559355, 2016).
macular holes (1 paper, 2015). A hole in the macula of the retina. "However a recent study reported elevated levels of PTX3 in vitreous from patients with central retinal vein occlusion compared to vitreous from patients undergoing surgery for macular hole." (PMID 26176960, 2015).
medullary thyroid cancer (1 paper, 2025). "This study evaluates PTX3 plasma levels in patients with non-medullary thyroid cancer (TC) compared to benign thyroid disease and investigates its tissue expression." (PMID 41373493, 2025).
meningitis (1 paper, 2023). A disorder characterized by acute inflammation of the meninges of the brain and/or spinal cord. "Our findings suggest that PTX3 does not cross the blood-brain barrier in patients without inflamed meninges, albeit we cannot conclude whether the PTX3 is produced intrathecally in patients with confirmed meningitis or passing from the blood through a permeable blood-brain barrier." (PMID 36862691, 2023). "We found PTX3 to be non-detectable or very low in the CSF in a control group despite clinical suspicion of meningitis and other inflammatory activity as indicated by elevated CRP and leukocytes in the blood." (PMID 36862691, 2023).
metastatic cancer (1 paper, 2017). A carcinoma which has spread from the original site of growth to another anatomic site. "These included genes which are implicated in inflammation and inflammatory responses to cancer (PTX3, IL8, TNFSF10, SERPINB13 and ANKRD1) and those involved in cell adhesion, cell migration and ECM degradation of importance in metastatic cancer (MMP12, MMP1 and ADAM19)." (PMID 28555042, 2017).
Miscarriage (1 paper, 2020). A pregnancy that ends at a stage in which the fetus is incapable of surviving on its own, defined as the spontaneous loss of a fetus before the 22th week of pregnancy. "Our results demonstrated a statistically significant increase in the levels of PTX-3 in women who had a miscarriage when compared with women of the control group." (PMID 32753622, 2020).
Myocardial necrosis (1 paper, 2015). Irreversible damage to heart tissue (myocardium) due to lack of oxygen after a heart attack (myocardial infarction). "Plasma levels of PTX3 seemed to reflect PTX3 gene expression in leukocytes, and plasma levels of MPO were significantly related to LVEF and myocardial necrosis." (PMID 28197227, 2015).
Nasal polyposis (1 paper, 2023). Polypoidal masses arising mainly from the mucous membranes of the nose and paranasal sinuses. "A previous study showed significant correlations between total IgE serum levels with the Sino-Nasal Outcome Test scores, Lund–Mackay computed tomography scan scores, and polyposis recurrence in 50 adult CRS patients with nasal polyposis, along with interleukin-17 and pentraxin-3 levels." (PMID 36838387, 2023).
nasopharyngeal carcinoma (1 paper, 2019). A carcinoma arising from the nasopharyngeal epithelium. "Not surprisingly in an intricate field such as the immune/inflammatory response, PTX3 has a dual character, one is good-protective against excessive inflammatory response, the other is harmful- antiangiogenic in cardiovascular diseases or inhibitor of phagocytosis in nasopharyngeal carcinoma." (PMID 31057548, 2019).
nephrocalcinosis (1 paper, 2018). Nephrocalcinosis is a disorder that occurs when too much calcium is deposited in the kidneys. "Genetic ablation of ptx3 in nephrocalcinosis un-susceptible B6;129 mice was sufficient to raise the oxalate nephropathy phenotype observed in susceptible strains." (PMID 30319631, 2018). "Our data showed that PTX3 is one of several endogenous inhibitors of stone formation in nephrocalcinosis and potentially in urolithiasis or other crystallopathies." (PMID 30319631, 2018). "In summary, the opsonin and immune regulator PTX3 also modulates CaOx crystal aggregation and adhesion to tubular cell membranes and is therefore one of several endogenous inhibitors of stone formation in nephrocalcinosis and potentially in urolithiasis or other crystallopathies." (PMID 30319631, 2018). "We had speculated that the long pentraxin PTX3, an opsonin known to interact with dead cells and other extracellular microparticles, would affect CaOx crystal aggregation and growth, central pathomechanisms in kidney stone disease and nephrocalcinosis." (PMID 30319631, 2018). "Next, the absence of nephrocalcinosis in Ptx3+/+ animals on B6;129 background 3 weeks after model induction prompted us to study issues of strain and sex dependency in this model." (PMID 30319631, 2018). "A detailed phenotype analysis revealed profound and progressive nephrocalcinosis-related tubular injury in Periodic acid-Schiff (PAS)-stained kidney sections with CaOx crystal plugs in dilated tubules in Ptx3−/− but not in Ptx3+/+ B6;129 mice." (PMID 30319631, 2018).
nephropathia epidemica (1 paper, 2021). "Recent study also indicated that plasma pentraxin-3 was highly correlated with PLT, Fib, APTT and other coagulation indicators, and which got a favorable predictive value for disease severity in patients with nephropathia epidemica." (PMID 34001041, 2021).
nephrotic syndrome (1 paper, 2016). A collection of symptoms that include severe edema, proteinuria, and hypoalbuminemia; it is indicative of renal dysfunction. "In clinical data, the urinary PTX3 levels were significantly higher in patients with hematuria (P = 0.047) and nephrotic syndrome (P = 0.019)." (PMID 26817892, 2016). "We also found that the differences of nephrotic syndrome, proteinuria, activity indices score, cellular crescents, interstitial inflammation cell infiltration, leukocyte infiltration and tubular atrophy, were more significant in PTX3 group than anti-ds-DNA antibody or C3 level groups." (PMID 26817892, 2016).
NK/T-cell lymphoma (1 paper, 2023). "Increased levels of the angiogenesis-associated proteins endostatin, neutrophil gelatinase-associated lipocalin (NGAL), and long pentraxin 3 (PTX3) have been observed in different types of NHL, in CLL and in NK/T-cell lymphoma." (PMID 37223632, 2023).
nodular goiter (1 paper, 2023). Goiter characterized by discrete tissue mass(es) that may or may not produce thyroid hormones. "On the other side, we observed significantly higher plasmatic levels of PTX3 in a cohort of patients who underwent thyroidectomy for nodular goiter." (PMID 37025408, 2023). "They did not observe differences of PTX3 plasmatic levels between nodular goiter group and control group, nor correlations between PTX3 levels and nodule characteristics." (PMID 37025408, 2023).
ocular infection (1 paper, 2018). "Microarray analysis and qPCR did not detect significant changes in ICAM1, CYR61, or PTX3 transcript levels in TLR4−/− following infection, suggesting the importance of TLR4 in eliciting a neutrophil response and complement activation following B. cereus ocular infection." (PMID 29661181, 2018).
ovarian disorder (1 paper, 2018). A disease involving the ovary. "Moreover, we discuss the emerging evidence that in humans altered PTX3 systemic levels, determined by genetic variations and/or low-grade chronic inflammation, can also impact the growth and development of the follicle and affect the incidence of ovarian disorders." (PMID 30555480, 2018).
ovarian endometriosis (1 paper, 2021). A non-neoplastic disorder characterized by the growth of endometrial tissue in the ovaries. "Thus, we speculate that the inhibition of LOX and PTX3 could provide a better treatment for ovarian endometriosis." (PMID 34202354, 2021).
ovarian tumor (1 paper, 2021). "In GSE27651 (6 normal ovary epithelial samples, 43 ovarian tumor samples), the AUC value of PTX3 was 0.925 (p < 0.001)." (PMID 33952272, 2021).
Pain (1 paper, 2022). An unpleasant sensory and emotional experience associated with actual or potential tissue damage, or described in terms of such damage. "The effects of pentraxin-3 and nectin-1 on the development of SNL-related neuropathic pain were investigated, and the potential link between pentraxin-3 and nectin-1 was characterized with reference to this pathological condition." (PMID 35625034, 2022).
parasitemia (1 paper, 2025). "Patients with undetectable parasitemia showed markedly lower PTX3 concentrations after therapy compared with patients who remained qPCR-positive (median PTX3: 1.545 ng/mL vs. 17.70 ng/mL; p = 0.01)." (PMID 41471254, 2025). "Pre-treatment PTX3 levels showed a significant positive correlation with parasite load (r = 0.39; p = 0.02), indicating that higher PTX3 concentrations accompany greater parasitemia." (PMID 41471254, 2025). "Additionally, little is known about the temporal kinetics of PTX3 after antigenic clearance in parasitic infections." (PMID 41471254, 2025). "Importantly, patients who achieved undetectable blood parasitemia at the immediate post-treatment time point exhibited significantly lower PTX3 concentrations than those who remained qPCR-positive, suggesting that PTX3 levels reflect residual parasitic burden as well as inflammatory activity." (PMID 41471254, 2025).
paroxysmal AF (1 paper, 2025). "In the group of N-CCS, the lowest values for pentraxin-3 are also found in those with SR, with a mean of 2256.81 ± 763.433, the highest values being observed in those with paroxysmal AF, with a mean of 3144.08 ± 1751.972." (PMID 40430046, 2025).
pneumococcal infection (1 paper, 2023). Infections with bacteria of the species streptococcus pneumoniae. "In a murine model of invasive pneumococcal infection, we observed that PTX3 genetic deficiency was associated with higher disease severity and higher respiratory tract inflammation." (PMID 37222419, 2023). "Thus, genetic deficiency in mice and gene polymorphisms in humans suggest that PTX3 plays an important role in the control of invasive pneumococcal infection." (PMID 37222419, 2023). "Defective resistance of Ptx3-deficient mice to invasive pneumococcal infection." (PMID 37222419, 2023). "In humans, PTX3 gene polymorphisms were associated with invasive pneumococcal infections." (PMID 37222419, 2023). "To dissect the mechanism by which PTX3 orchestrates the modulation of inflammation during pneumococcal infection, we first evaluated the level of neutrophil chemoattractants." (PMID 37222419, 2023). "Accordingly, neutrophil depletion by anti-Ly6G was used to assess the role of these cells in PTX3-mediated protection against pneumococcal infection." (PMID 37222419, 2023). "Endothelial cells were described as an important source of PTX3, thus we evaluated their contribution to PTX3 production during pneumococcal infection." (PMID 37222419, 2023). "The general aim of this study was to assess the role of the long pentraxin PTX3 in invasive pneumococcal infection." (PMID 37222419, 2023). "Ptx3−/− mice presented more severe invasive pneumococcal infection." (PMID 37222419, 2023). "Thus, the defective control of invasive pneumococcal infection observed in Ptx3−/− mice is due to unleashing P-selectin-dependent recruitment of pneumococcus-promoting neutrophils." (PMID 37222419, 2023). "The present study was designed to assess the role of PTX3 in invasive pneumococcal infection." (PMID 37222419, 2023). "The involvement of PTX3 in the control of selected respiratory pathogens and in the modulation of infection prompted us to investigate the role of this molecule in the control of pneumococcal infections." (PMID 37222419, 2023). "In a murine model of invasive pneumococcal infection, PTX3 was strongly induced in non-hematopoietic (particularly, endothelial) cells." (PMID 37222419, 2023). "PTX3, mainly produced by stromal non-hematopoietic cells during pneumococcal infection, modulated neutrophil recruitment by dampening P-selectin-dependent neutrophil migration." (PMID 37222419, 2023). "Non-hematopoietic cells are a major source of PTX3 during pneumococcal infection." (PMID 37222419, 2023). "During pneumococcal infection, we did not observe any difference in the levels of PTX3 in the respiratory tract and in the serum of WT mice receiving bone marrow from Ptx3−/− or WT animals, while no PTX3 was measured in Ptx3−/− mice receiving WT or Ptx3−/− bone marrow." (PMID 37222419, 2023).
pneumococcal meningitis (1 paper, 2023). An acute purulent infection of the meninges and subarachnoid space caused by Streptococcus pneumoniae, most prevalent in children and adults over the age of 60. "One patient with pneumococcal meningitis had very high CSF PTX3 at 26964 ng/ml." (PMID 36862691, 2023).
Premature rupture of membranes (1 paper, 2021). Premature rupture of membranes (PROM) is a condition which occurs in pregnancy when the amniotic sac ruptures more than an hour before the onset of labor. "The highest PTX3 concentrations were observed in children with infection in the presence of premature rupture of membranes (PROM)." (PMID 34307663, 2021).
primary hyperoxaluria type 1 (1 paper, 2018). A rare disorder of glyoxylate metabolism characterized by the accumulation of oxalate due to a deficiency of the peroxisomal hepatic enzyme L-alanine: glyoxylate aminotransferase (AGT). "We selected the B6;129-Ptx3tm1Mant mice that has global PTX3-deficiency to unravel the role of this pentraxin in CaOx crystal aggregation-related disease, i.e., in a model resembling the kidney phenotype of primary hyperoxaluria type I or other forms of progressive nephrocalcinosis." (PMID 30319631, 2018).
prion disease (1 paper, 2014). A transmissible disease that is caused by a protein that is able to induce abnormal folding of normal cellular proteins, leading to characteristic spongiform brain changes, which are associated with neuronal loss without an inflammatory response. "We have previously shown that a number of typical acute phase proteins serum amyloid A, complement C3, pentraxin 3, and α2-antiplasmin are induced in the brain of animals with prion disease, but there is no induction of message in the liver despite the presence of systemic deposition of PrPSc." (PMID 24366862, 2014).
pulmonary fungal disease (1 paper, 2024). "Studies have linked elevated serum PTX-3 or certain PTX-3 polymorphisms with invasive pulmonary aspergillosis or pulmonary fungal disease." (PMID 39151096, 2024).
pyelonephritis (1 paper, 2019). An inflammatory process affecting the kidney. "Serum and urinary PTX3 levels are increased in pyelonephritis patients and correlated with parameters of disease severity." (PMID 31031772, 2019). "After antibiotic treatment PTX3 levels were reduced in plasma of patients with CAP, or in urine of pyelonephritis patients." (PMID 31031772, 2019).
retinal diseases (1 paper, 2021). "Here, we discuss current viewpoints on PTX3 and retinal diseases, with a focus on AMD and DR, the roles therein proposed for this pentraxin, and their implications for the development of new therapeutic strategies." (PMID 35069222, 2021).
SARS-CoV infection (1 paper, 2013). "Similarly, DUSP8, IL6, CXCL10, and NFKBIA are up-regulated in SARS patients, while PTX3 and CXCL2 have been shown to be involved in SARS-CoV infection." (PMID 23935999, 2013).
scrub typhus (1 paper, 2014). Scrub typhus is a rare dust mite-borne infectious disease caused by the Orientia tsutsugamushi bacterium and characterized clinically by an eruptive fever which is potentially serious. "Thus, although plasma levels of CRP, PTX-3 and IL-6 were markedly raised in scrub typhus patients, similar levels were found in infectious disease controls." (PMID 24516677, 2014).
septic arthritis (1 paper, 2025). "The findings of our study demonstrated that, although routinely used biomarkers such as serum CRP and synovial WBC remain valuable in diagnosing septic arthritis, incorporating novel biomarkers, such as PTX3, IL-6, and presepsin, could enhance diagnostic accuracy." (PMID 40807041, 2025). "Although identifying novel biomarkers, such as synovial PTX3, is essential for diagnosing septic arthritis, the routinely used biomarkers still play a crucial role in detecting septic arthritis." (PMID 40807041, 2025). "PTX3 is best suited for ruling out septic arthritis due to its high sensitivity and NPV, whereas presepsin is more useful for confirmation, given its specificity and PPV." (PMID 40807041, 2025). "The serum CRP, synovial WBC, and PTX3 levels were significantly higher in the septic arthritis group than in the non-septic arthritis group (p = 0.022, p = 0.023, and p = 0.017, respectively)." (PMID 40807041, 2025). "The study aimed to evaluate the diagnostic performance of routinely used and novel biomarkers, including serum C-reactive protein (CRP), synovial white blood cells (WBC), pentraxin-3 (PTX3), interleukin-6 (IL-6), and presepsin, in distinguishing septic from non-septic arthritis." (PMID 40807041, 2025). "Notably, different biomarker combinations offered distinct diagnostic advantages: PTX3 provided the highest sensitivity and NPV, making it helpful in ruling out septic arthritis, whereas presepsin offered the highest specificity and PPV, supporting its role in confirmatory diagnosis." (PMID 40807041, 2025).